TNF (tumor necrosis factor)
Diseases named in the same sentence as TNF in open-access papers (continued):
Sharing a sentence is not in itself a finding about the gene and the disease.
infection (continued). "It is important to note that TNF KO mice died at 7–8 weeks post-infection, so we were unable to evaluate the frequency of CD3+ myeloid subpopulations at 14 weeks post-infection in TNF KO." (PMID 31787969, 2019). "Co-infected mice expressed elevated IFN-γ and TNF-α levels over P. berghei or T. brucei mono-infected group suggesting active response against secondary infection." (PMID 31687034, 2019). "Infection of IL-10−/− mice with C. jejuni is characterized by increased levels of pro-inflammatory cytokines (TNF-α, IL-1β, IL-6, IFN-γ and IL-22) and infiltration of inflammatory cells in the colon." (PMID 31427597, 2019). "TNF-α, IL-1β, and IL-6, 3 important pro-inflammatory cytokines, are widely accepted as downstream factors subsequent to pathogen infection and demonstrated a similar pattern." (PMID 31447841, 2019). "In the CNS of Ifnar1−/− mice, IFN-α1, IFN-β, TNF, IL-1α, IL-1β, and IL-6 mRNA levels were increased at day 4 post infection when compared with sham-injected controls." (PMID 31511023, 2019). "Among all genes activated in the brain tissue upon infection, IFN-γ and TNFα were the most highly transcribed cytokines associated with HPAI AB14 (H5N1) infection." (PMID 30813415, 2019). "Serum concentrations of TNF-α were significantly higher on the third and sixth days of infection when compared to the PBS control, for both A/J C5+/+ and A/J C5−/− mice." (PMID 31687410, 2019). "In the livers of infected WT mice, only TNF mRNA was significantly increased at day 6 post infection, whereas mRNA levels for the other cytokine genes were comparable to the sham-injected mice and IFN-γ mRNA was undetectable." (PMID 31511023, 2019). "At 24 h after infection, TNF-α ELISA findings showed a significantly greater level in the plasma of pfbA mutant strain-infected mice as compared to the wild-type strain-infected mice." (PMID 31482074, 2019). "For instance, in the RV144 trial, CD4+ T-cells secreting IL-2, TNF-α, IFN-γ, IL-4, and CD154 in response to HIV-1 envelope peptides were associated with lower infection rates in vaccine recipients." (PMID 31382453, 2019). "Circulating leukocytes i.e., neutrophils and monocytes are recruited to the source of infection and release TNFα, a potent endothelial cell activator." (PMID 31447831, 2019). "They observed inhibition of some of the most critical cytokines for parasite growth and the establishment of infection, including granulocyte-macrophage colony-stimulating factor, interleukin-4 (IL-4), IL-10, and tumor necrosis factor (TNF)." (PMID 30881596, 2019). "The results indicated that the mRNA expression of IL-2, IL-6, and TNF-α induced by Salmonella CVCC541 infection was significantly inhibited after the JH-3 treatment (p < 0.05)." (PMID 30736473, 2019). "The administration of a TNF-α agonist, prior to infection with A. fumigatus, is able to increase the survival of mice." (PMID 31551957, 2019). "This process is amplified by T cell activation and IFN-γ release, which promotes macrophages to achieve a whole activated/M1 polarization and consequently increases TNF-α and NO secretion to control the infection." (PMID 31603063, 2019). "Particularly, TNF-α and IL-1β are produced in large amounts by polymorphonuclear leukocytes and activated macrophages during the initial stages of infection." (PMID 31847340, 2019). "Comparisons of infection rates between anti-IL-6R and antitumor necrosis factor α (TNFα) therapy have also been conducted, with some observational cohort studies finding a higher infection rate in tocilizumab." (PMID 31261772, 2019). "In the current study, the release of the inflammatory cytokines IL-6, TNF-α, IL-1β, and IL-12 in the serum of the TG mice was reduced compared with that of the WT mice after infection with S. Typhimurium or administration with LPS." (PMID 31379864, 2019). "Significantly increased production of TNF-α, IL-6, and IL-1β was detected after infection with the wild-type strain compared to that with the ΔbceR strain." (PMID 30728810, 2019).
infection (continued). "After infection, when compared with the lean group, the contents of TNF-α, IL-1β, IL-6, IL-8, resistin, and leptin in the lean-E." (PMID 31085802, 2019). "To determine the tissue response to infection with N. gonorrhoeae, we have measured the amount of pro-inflamatory cytokines IL-6 and TNFα, and chemokine IL-8 released into the apical medium 24 h post infection." (PMID 31417529, 2019). "Microglia/macrophages are known to represent a major source of ROS in response to infection or pro-oxidant cytokine stimulation such as interleukin-1 (IL-1) and tumor necrosis factor (TNF)." (PMID 31262031, 2019). "Tumor necrosis factor alpha (TNF-α) and interleukin-1β (IL-1β) levels were highly induced following infection with the WT strain compared to infection with strain ΔanvM." (PMID 31337721, 2019). "During infection, mice infected with a highly virulent C. neoformans strain show significantly lower TNF-α expression in the lungs compared to mice infected with less virulent C. neoformans strain." (PMID 31404168, 2019). "In a murine model, sPPG has been shown to inhibit TNF-α release to facilitate the establishment of the infection." (PMID 31603063, 2019). "More interestingly, the infection of DCs with Chlamydia would induce the production of the cytokines TNF-α, IL-4, and IL-10 facilitating Th2 immunity and suppressing Th1 development." (PMID 31333596, 2019). "To investigate the role of PfbA in pneumococcal pathogenesis, we infected mice with S. pneumoniae strains intratracheally and compared bacterial CFUs and TNF-α levels in BALF from mice at 24 h after infection." (PMID 31482074, 2019). "To study the influence of B1R/B2R on the inflammatory response at the primary site of infection, we measured cytokine (tumor necrosis factor (TNF) α, interleukin (IL)-1β, and IL-6) and chemokine (CXCL1, CXCL2, and CCL2) levels in whole lung homogenates." (PMID 30874974, 2019). "The blood of infected animals was collected 5–40 days after the infection for the evaluation of plasmatic levels of TNF-α and IL-1β over the course of the disease." (PMID 31138231, 2019). "Our infection model demonstrated that circulating cytokines TNF, IL-1β, MCP-1, and IFN-γ were largely increased at both 24 and 48 hpi as a severe systemic inflammatory response." (PMID 30837977, 2019). "Studies on DCs activated by different maturation factors showed that iDCs and CD40L-induced mDCs were more susceptible to productive infection and lead to cis-infection, while LPS and TNF-α-induced mDCs mediated efficient trans-infection of CD4+ T cells." (PMID 31708924, 2019). "TNF-α and IL-6 are the two major inflammatory cytokines, and they are promptly and transiently produced in response to infection and tissue injury." (PMID 31671698, 2019). "Colonic secretion of TNF-α and nitric oxide was increased exclusively upon infection with WT and ΔcadF strains (p < 0.001)." (PMID 31131028, 2019). "Endotoxin tolerance mainly affects macrophages and drastically reduces their TNF production but strongly activates their bactericidal activity in response to infection." (PMID 31269748, 2019). "In these diseases, NF-κB occurs largely in response to cytokines such as IL-1β and TNF-α or by infection with viruses during exacerbations." (PMID 32038638, 2019). "In order to further explore the possibility that TNF-α plays a role in enhanced MCMV-induced liver damage in Gal-3 deficient animals, pharmacological inhibition of TNF-α with infliximab was done before infection." (PMID 30800112, 2019). "Again at 48 h post-infection, significantly lower levels of IL-1Ra, IL-6, IL-8, IL-10, IL-12p40, GM-CSF, TNF-α, VEGF, MCP-1, and MIP-1b were observed in the ESRD group." (PMID 31875015, 2019). "LPS is predominantly involved in stimulating TNFα mRNA expression and production of this cytokine following infection of monocytes." (PMID 30620769, 2019).
infection (continued). "We also found positive prognostic associations with elevated levels of TNFα and MCP-1, immune mediators involved in Th1 and Th2 immunity, respectively, but also in anti-parasitic/infection responses." (PMID 31069161, 2019). "IL-1β and TNFα are central cytokines in immune cell communication and activation and as such recruit innate immune cells to the site of infection and cell damage." (PMID 31273197, 2019). "TNFα participates in biological effects including cell growth, cell differentiation, and cytotoxicity and, most importantly, in our study, anti-infection." (PMID 31847332, 2019). "Notably, the strongest association was with IFN-γ and TNF-α double-cytokine producing cells which represent an effector memory population, supporting our hypothesis that parameters measured post-infection correlate with MGIA responses because both are measuring re-stimulated memory responses." (PMID 31998295, 2019). "Conversely, if TNFα/CHX was added 2 h post infection, a drastic and significant drop in the percentage of cells engaged in apoptosis was observed." (PMID 31671831, 2019). "In fact, it is rational to suppose that TNF-α and IL-1β produced at the infection primary foci explain the hyperalgesia observed before spinal cord glia activation." (PMID 31138231, 2019). "Other conventional pigs infected with Salmonella Typhimurium X4232 showed increased serum levels of IL-8, TNF-α and IL-10 two days post-infection." (PMID 31540295, 2019). "The level of the pro-inflammatory cytokines TNF-α, IL-1β and IL-6 and the anti-inflammatory cytokine IL-10 was quantified at 10 h post-infection in the supernatants of infected MDM." (PMID 31694333, 2019). "In the model, an infection leads to activation of immune cells followed by secretion of pro-inflammatory cytokines, e.g. TNF-α, IL-1β, and IL-6." (PMID 31791247, 2019). "A co-expression analysis of MHC class II+TNF-α+ in BMM cells confirmed the observed phenotypical alteration upon infection with IOE." (PMID 31575880, 2019). "Infection with 107 of virulent and attenuated (L. interrogans serovar Copenhageni) and saprophytic (L. biflexa serovar Patoc), induced significant increase of TNF-α expression in murine macrophages (p <0.0001) compared to control." (PMID 31800570, 2019). "In line with an increased infection rate, smoking reduced 25OH vitamin D3 (immune-modulatory), IL-1β, IL-6, TNF-α, and IFN-γ serum levels." (PMID 30909629, 2019). "Tc infection increased plasma levels of IL-1β as well as other HPA axis-activating cytokines such as TNF-α, IFN-γ, or IL-6." (PMID 31998227, 2019). "At the late phase of infection (72 h post-infection), levels of IL-1Ra, IL-6, IL-8, IL-10, IL-12p40, GM-CSF, TNF-α, MCP-1, and MIP-1b still remained significantly low for ESRD group, as compared to control group." (PMID 31875015, 2019). "Initially the TNF-α concentration was much lower in the NC group than the other groups, but all groups showed a decreasing concentration post infection (experiment day 5)." (PMID 31655595, 2019). "As we known, hs-CRP is a reactant involved in the acute-phase response and rapidly increases in the presence of infection or inflammation, which is stimulated by the release of proinflammatory cytokines, including IL-1, IL-6 and TNF-α." (PMID 31296192, 2019). "IL-4, IL-1β, and tumor necrosis factor alpha (TNF-α) remained at background levels at all times of the infection." (PMID 30804100, 2019). "The cytokines production in response to AIEC infection was similar across the three groups (CD, UC and controls) except for TNF-α release between UC and CD patients." (PMID 31694333, 2019). "At 24 h, 48 h, and 72 h post-infection, significantly lower levels of IL-1Ra, IL-6, IL-8, IL-10, IL-12p40, TNF-α, MCP-1, and MIP-1b were detected in ESRD group." (PMID 31875015, 2019). "The induction of TNF-α, IL-6, and IL-1β was maintained at relatively low levels compared with infection with L. monocytogenes or treatment with LPS." (PMID 31877174, 2019).
infection (continued). "We predicted that TNF-α production would differ between local and systemic sites due to different immune cell populations being involved and their proximity to the site of infection." (PMID 31368489, 2019). "Stx-producing infection also contributes to release of inflammatory cytokines and cytokine-mediated events, particularly TNFα, platelet activation, increased procoagulant tissue factor activity on glomerular endothelial cells, and activation of complement." (PMID 31881024, 2019). "In a small number of patients we also evaluate the expression of these cytokines after 24 h of infection and as expected there was a decrease in the intracellular expression of TNF and IL-10 as these cytokines are predominantly detected early after infection." (PMID 31119102, 2019). "Mice infection with a human and food C. jejuni isolates induced strong pro-inflammatory responses with elevated levels of IL-12, TNF-α and IFN-γ." (PMID 30922352, 2019). "After infection, the maximal TNF-α and IL-10 response generated by the chimera was also directed against the FMLQILDFYTKVYE epitope while all other epitopes only induced TNF-α secretion." (PMID 31024556, 2019). "For example, infection with L. baziliensis promotes the infiltration of intermediate monocytes that express TNF and IL1β and enhance the inflammatory response in human patients." (PMID 31608245, 2019). "The primary outcome was the odds of infection in the TNF-alpha inhibitor group compared to the control groups." (PMID 30658717, 2019). "On the third day after infection, high levels of proinflammatory cytokines TNF, INF-γ and IL-6 and chemokine MCP-1 were detected in the serum of both infected groups." (PMID 31050676, 2019). "In our study, the macrophages from UC patients seem to be more reactive in terms of TNF-α secretion following infection compare to CD patients." (PMID 31694333, 2019). "Previous studies showed low levels of IL-1 in plasma after experimental infection with S. suis, in comparison with other important pro-inflammatory cytokines such as TNF or IL-6." (PMID 31262357, 2019). "Increased sytemic levels of TNF-α and IL-10 indicated the severity of infection and poor prognosis for survival in preterm infants and adults." (PMID 31434337, 2019). "Other pathogens such as Escherichia coli (ETC, EPEC, EIEC, etc.), Shigella, Salmonella, and Yersinia colonize the gut and lead to the synthesis of proinflammatory molecules as TNF-α and IL-18, which are produced by macrophages in response to the infection." (PMID 31481953, 2019). "Meanwhile, upon infection, the expression of IL-1β and TNF were decreased with epinecidin-1 plasmid electroporation, supporting the protective role of Epi-1 against mortality caused by overexpression of immune-related genes." (PMID 31824449, 2019). "A 6-h infection at a multiplicity of infection (MOI) of 100 in THP-1s gave a level of IFN-I production comparable with that of an 18-h infection at an MOI of 1 in primary monocytes, and these infection regimes led to maximal TNFα production." (PMID 31558608, 2019). "Macrophages in BALF remained markedly high during infection, with concomitant increase in pro-inflammatory cytokines (TNF-α, IL-1β, IFN-γ, and IL-6), compared HAdV-3 infection." (PMID 30626350, 2019). "The secondary outcomes included rate and type of infection; cause of mortality; and levels of AST, ALT, bilirubin, MDF, and TNF-α at the end of one month." (PMID 31516791, 2019). "For example, TNF-α aids clearance of respiratory syncytial virus (RSV) during the early phase of infection but prolonged production is suggested to exacerbate tissue damage." (PMID 31100860, 2019). "Confirming that, strong Th1 responses were disclosed by the elevated IFN-γ/IL-10 and TNF-α/IL-10 ratios promoted by the F3 vaccine, before infection and detected in the F1 vaccinated and infected controls after challenge with L. (V.)braziliensis." (PMID 31024556, 2019).
infection (continued). "During infection, host innate immune cells release cytokines (primarily IL-1, IL-6 and TNFα) which act on the hypothalamus in the brain and induces a fever response." (PMID 31358780, 2019). "The levels of inflammatory mediators associated with airway inflammation, including IL-1β, TNF-α, IFN-γ, and IL-6, were also clearly elevated in BALF at 3, 5, and 7 days post HAdV-3 and HAdV-7 infection." (PMID 30626350, 2019). "During the first and second weeks of infection TNF-α expression was higher in mice infected at ZT3 compared to mice infected at ZT15; however, this difference was not significant." (PMID 31388084, 2019). "After overnight infection, all cell types produced comparable amounts of NF-κB-dependent cytokines, namely TNF IL-6 or IL-12p40, whatever the rBCG strain used for stimulation." (PMID 31921172, 2019). "According to the linear regression model, a time-dependent increase in the amount of TNF-α during the infection was demonstrated (R = 0.79; p < 0.001)." (PMID 31086416, 2019). "Results show that, compared to r19F-infected animals, r19FCX4C-infected animals produced significantly lower levels of cytokines/chemokines (IFN-γ, MCP-1, and TNF-α or an antiviral protein (MX1) at day five post infection." (PMID 31330970, 2019). "A further study examining the influence of SRLV infection on TNF-α gene expression found the level of TNF-α mRNA to be reduced in macrophages seven days after experimental infection compared to mock-infected control cells." (PMID 31775763, 2019). "Inflammation is a complex biological response to harmful stimuli, tissue injury, or infection and produced a number of proinflammatory mediators, such as TNF-α and IL-6." (PMID 31886241, 2019). "At 24 h post-infection, the mRNA level of TNF-α, IL-1β, and IL-6 were measured by relative quantitative RT-PCR normalized against peptidylprolyl isomerase A (PPIA), a molecule that has been previously used for internal control." (PMID 31561412, 2019). "Before infection with E. coli, TNF-α, IL-6, resistin, and leptin contents of the DIO group were significantly higher (p<0.05) than those of the lean group." (PMID 31085802, 2019). "Upon infection, inflammatory monocytes exit the BM and home to the lamina propria where they differentiate into TNF-α/inducible nitric oxide synthase (iNOS)-producing (Tip)-DC that control infection." (PMID 31354722, 2019). "At 72 h post-infection, the production of IL-12p70 and TNF-α was significantly enhanced in BMDMs treated with Rv3463 when compared to non-treated infected cells or cells stimulated with other antigens." (PMID 30862819, 2019). "T. cruzi-stimulated SMC taken from mice treated with 3-HK plus ITE at the acute phase of the infection (day 22 pi) secreted significantly lower amounts of TNF and IFN-γ and higher amounts of IL-10 than those from untreated mice." (PMID 30984194, 2019). "Infection with the ∆stir-2 mutant increased the expression of IL-6, IL-1β, and TNF-α at 18, 24, and 48 hpi, respectively, compared with macrophages infected with the wild-type SC09 strain or the ∆stir-2 + pSTIR-2 mutant strain." (PMID 31500298, 2019). "Together, these data reinforce the idea that the up regulation of these receptors, after infection with leishmania, activates the monocytes to produce TNF and IL-10." (PMID 31119102, 2019). "While at day 5 of infection TNF was significantly higher in spleen of control mice, in general during infection the expression of cytokine was variable within groups and levels were not significantly different between the two strains of mice." (PMID 31242184, 2019). "Expression of ICAM-1 in human IECs is upregulated following infection with invasive bacteria and stimulation with TNF-α and IFN-γ." (PMID 31035617, 2019). "A meta-analysis carried out in the United States (US) concluded that the use of Anti-TNF therapy increased the chance of the occurrence of any infection by 20% and serious infections by 40%." (PMID 31584996, 2019).